REN (renin)
Diseases named in the same sentence as REN in open-access papers (continued):
Sharing a sentence is not in itself a finding about the gene and the disease.
Hypertension (continued). "ACE inhibitors (ACEi) and ARBs that affect the renin–angiotensin–aldosterone system (RAAS) are commonly recommended for patients with hypertension." (PMID 32585855, 2020). "In the crude analysis, sUmod was inversely related to renin in the total study group (β -0.14 ± 0.03; p < 0.001) and in participants with arterial hypertension (β -0.13 ± 0.04; p = 0.002)." (PMID 32764816, 2020). "Dialysis patients experience abnormal response of the renin-angiotensin system (RAS), leading to higher incidence of hypertension, which is one of the leading causes of CV disease and mortality." (PMID 33029520, 2020). "In both normotensive and hypertensive subjects, 1,25(OH)2D serum levels are inversely associated with PRA (plasma renin activity), suggesting a potential role of vitamin D in hypertension via renin regulation." (PMID 32911795, 2020). "Hypertension can lead to left ventricular hypertrophy and myocardial fibrosis and can trigger arrhythmia by activating the sympathetic nervous system and the renin–angiotensin–aldosterone system." (PMID 32987834, 2020). "The brain renin-angiotensin system is an important element of hypertension programming during fetal life." (PMID 32446297, 2020). "VDR null-mice exhibited increased concentrations of renin and angiotensin II leading to hypertension." (PMID 32164233, 2020). "This phenomenon is a result of the accumulation of blood or urine in the perinephric or subcapsular space, resulting in compression of renal parenchyma, microvascular ischemia, alteration in the renin-angiotensin apparatus, and high renin hypertension." (PMID 32884853, 2020). "ET-1 production is initiated by endothelial dysfunction and further promotes hypertension and proteinuria while suppressing renin release." (PMID 32599856, 2020). "Renin and CT-proET-1 were significantly higher in participants with hypertension, whereas aldosterone was similar in both groups." (PMID 32764816, 2020). "All cases in our study presented with typical symptoms of JGCT, including hypertension, hyperaldosteronism, high plasma renin, high plasma angiotensin II and hypokalemia." (PMID 32441904, 2020). "The role of the renin-angiotensin system in hypertension and end-organ damage has long been recognized." (PMID 32728402, 2020). "Hypertension is common, which occurs in 80% of cases due to stenosis of the renal arteries resulting in activation of renin-angiotensin- aldosterone system." (PMID 33298181, 2020). "This miRNA is taken up by JG cells to activate renin production, identifying a mechanism of inflammation-induced hypertension." (PMID 32968066, 2020). "Enalaprilat is used for high-renin hypertension and is the only angiotensin-converting enzyme inhibitor available as an IV formulation." (PMID 33194923, 2020). "Hypertension, the major risk factor for CHD, is related to the activation of renin–angiotensin system (RAS) (Te Riet, Esch, Roks, Meiracker, & Danser, 2015)." (PMID 32090477, 2020). "OSA and hypertension share many common factors in pathophysiology, such as gender, obesity, unhealthy lifestyle, impaired quality of sleep, renin-angiotensin system, and increased fluid distribution." (PMID 32582500, 2020). "The pathophysiology in this case was considered to be mainly hypertension and vascular endothelial injury with renin-angiotensin-aldosterone system (RAAS) activation." (PMID 32728521, 2020). "In turn, increased renin results in the activation of the renin-angiotensin system that contributes to the pathogenesis of hypertension." (PMID 32328302, 2020). "Noncoding RNAs have also been found to participate in the programming of hypertension, including several microRNAs that modify genes related to steroidogenesis and the renin–angiotensin–aldosterone pathway." (PMID 32054074, 2020). "Endocrinopathy such as IR and high renin-angiotensin activity was documented in several previous reports investigating the pathogenesis of hypertension and BA." (PMID 33330745, 2020).
Hypertension (continued). "Excessive activation of the tissue renin–angiotensin system through angiotensin II (Ang II) type 1 receptor (AT1R) plays a pivotal role in the pathogenesis of hypertension and related organ injury." (PMID 32112267, 2020). "Typical symptoms of JGCT include hypertension, hypokalemia, and renal mass with renin secreting leading to hyperaldosteronism." (PMID 32441904, 2020). "The TTRhRen mice are the transgenic animals, which the human renin cDNA transfected into their genome, and they develop renin-dependent hypertension." (PMID 32566684, 2020). "The atypical type presents with hypertension and renal mass with a normal renin secretion and serum potassium." (PMID 32441904, 2020). "The loss of nephron mass and the consequent nephron hyperfiltration can lead to the activation of the renin‐angiotensin system, hypertension and the subsequent glomerulosclerosis." (PMID 33043579, 2020). "Knockout of Cx40 in renin-secreting cells led to increased renin level and renin-dependent hypertension, which was presumably due to dysfunction of gap junction-mediated negative regulatory signals." (PMID 32585970, 2020). "In mice, germline vitamin D receptor (VDR) knockouts exhibit hypertension and cardiac hypertrophy due to upregulation of renin promoter activity and RAS activation." (PMID 32968066, 2020). "These mutations inhibit degradation of ENaC and excessive sodium absorption culminating to hypertension, hypokalemia, metabolic alkalosis, and a low plasma renin and aldosterone." (PMID 33194923, 2020). "Renin production is reported to increase when there is partial occlusion of the renal artery, which would explain the hypertension and decreased uteroplacental circulation resulting in growth restriction." (PMID 31564080, 2020). "In the kidney, the stimulation of renin production by the collecting duct (CD-renin) contributes to the development of hypertension." (PMID 33281610, 2020). "Among our study population, hypertension was the most prevalent cardiovascular comorbidity and it was more likely treated with renin–angiotensin aldosterone system (RAAS) inhibitors, regardless of gender differences." (PMID 33375676, 2020). "Hypertension combined with hyperaldosteronism and hypokalemia secondary to high plasma renin activity are the typical symptoms of juxtaglomerular cell tumor." (PMID 32441904, 2020). "Our study was aimed at evaluating the genetic contribution to the onset of pathophysiological arterial hypertension by measuring plasma renin activity in the Shors, minor indigenous peoples living in the south of Western Siberia." (PMID 32293282, 2020). "This includes renin-angiotensin-aldosterone system inhibitors in patients with hypertension and proteinuria and regular follow-up to monitor disease progression and hypertension." (PMID 32724739, 2020). "Several putative hypertension-related genes have been identified, mainly affecting the renin-angiotensin-aldosterone system." (PMID 33195469, 2020). "A number of researchers have identified various endotypes of hypertension: low-renin hypertension, salt-and-stress-sensitive hypertension, hypertension associated with obesity, etc.." (PMID 32099839, 2020). "Inappropriate activation of the renin-angiotensin-aldosterone system (RAAS) is an important factor in the development of hypertension." (PMID 33014117, 2020). "On the other hand, regulatory T-cells (a lymphocyte sub-type) is a known role player in the development of hypertension through its role in the renin–angiotensin system." (PMID 32849535, 2020). "Overactivation of the renin-angiotensin system (RAS) – a central physiological pathway involved in controlling blood pressure (BP) – leads to hypertension." (PMID 33329061, 2020). "One popular physiological mechanism of hypertension is the renin-aldosterone-angiotensin system (RAAS)." (PMID 32726971, 2020).
Hypertension (continued). "It is well established that increased SNS outflow and enhanced renin-angiotensin system (RAS) activity are common features of hypertension and various pathological settings that predispose individuals to hypertension." (PMID 32242284, 2020). "Severe hypertension in this Ren2 animal model over 12 weeks, resulting from upregulation of the renin angiotensin aldosterone axis, led to significant hypertensive nephrosclerosis with glomerulosclerosis and renal cortical interstitial fibrosis." (PMID 32441493, 2020). "In fact, drugs acting through the renin-angiotensin-aldosterone system have been shown to be renoprotective in adults and are recommended for patients with both diabetes and hypertension." (PMID 31924175, 2020). "Physiological dysfunction in the endothelium triggers the production of endothelin-1 (ET-1), which further induces hypertension and proteinuria and suppresses renin release." (PMID 32599856, 2020). "It encompasses a group of conditions characterized by early-onset severe hypertension, hypokalemia, metabolic alkalosis, and a high plasma aldosterone/renin ratio (ARR>20)." (PMID 33569358, 2020). "Renal vascular model is suitable for demonstrating the mechanism of renin and sympathetic nerve system on target organ injury in hypertension." (PMID 32099670, 2020). "Emerging research suggest that vasopressin plays important role in the progression of CKD and hypertension via stimulation of the renin angiotensin aldosterone system (RAAS) leading to vasoconstriction and higher systemic and glomerular blood pressure." (PMID 32033584, 2020). "Accordingly, augmentation of NO bioavailability contributes to reduce the development of hypertension due to decreased CD-renin secretion." (PMID 33281610, 2020). "The i.c.v. administration of Nesfatin-1 in animal studies increased plasma renin, catecholamine, and vasopressin which resulted in hypertension, too." (PMID 31339256, 2020). "The AHR pathway has been reported to interact with nitric oxide (NO), the renin–angiotensin system (RAS), and gut microbiota, which are crucial mechanisms underlying hypertension, to affect blood pressure (BP)." (PMID 32604820, 2020). "In this review, the treatment options that target the renin–angiotensin system (RAS) in the management of hypertension were summarized, with special emphasis on ethno-medicinal plants and their influence on the ACE1 RAS pathway." (PMID 32366012, 2020). "The renin-angiotensin system plays a very critical role in hypertension, diabetes, and kidney and heart diseases." (PMID 32685221, 2020). "This renal hypoperfusion leads to volume overload and severe hypertension seen in acute pulmonary edema due to the activation of the renin-angiotensin system." (PMID 32399343, 2020). "The present study is aimed at assessing the effects of different antihypertensive drug combination regimens involving renin-angiotensin-aldosterone system (RAAS) inhibitors on CABP indices in Indian patients with hypertension." (PMID 32983258, 2020). "Sex differences in hypertension is postulated to be a result of the role of the immune system in mediating sex differences in hypertension where kidneys, the renin-angiotensin system, and developmental programming known to play a role." (PMID 32550967, 2020). "Mating of female transgenic mice expressing angiotensinogen with males expressing renin leads to a preeclampsia-like phenotype with hypertension, proteinuria and kidney injury." (PMID 33067549, 2020). "Potential mechanisms by which UA may cause hypertension have been previously published but include the ability of UA to induce intracellular and mitochondrial oxidative stress and decrease endothelium nitric oxide bioavailability as well as the intracellular renin-angiotensin system (RAS)." (PMID 33072398, 2020). "The patients with typical type can present with typical JGCT symptoms of hypertension, hypokalemia, hyperaldosteronism, and high renin." (PMID 32441904, 2020).
Hypertension (continued). "Clinically, there is an abundance of pharmacological treatments for hypertension that directly target the renin angiotensin aldosterone system (incl." (PMID 32194403, 2020). "In turn, genomic DNA hypomethylation can promote the expression of certain genes, thereby activating the renin-angiotensin-aldosterone system and leading to hypertension." (PMID 33145104, 2020). "The renin-angiotensin system is activated by chronic inflammation in hypertension, diabetes, obesity, and cancer." (PMID 33256258, 2020). "Substitution of Cx40 with Cx45 in mice with high plasma renin and hypertension led to significantly reduced hypertension, thus pointing to role of Cx45 in blood pressure control." (PMID 33172216, 2020). "Obesity-related renal alterations, such as hemodynamic changes, impaired natriuresis, and activated renal (and/or systemic) renin-angiotensin-aldosterone system, have been presumed to contribute to the maintenance or development of hypertension." (PMID 32929357, 2020). "Emphasis is given to the role of the renin-angiotensin system and its inhibitors, given the crucial role that this system plays in both viral transmissibility and the pathophysiology of arterial hypertension." (PMID 33329052, 2020). "The central role of the renin-angiotensin-aldosterone system in the development of essential hypertension is well-known." (PMID 32792976, 2020). "ACE2 is highly expressed in the heart as well, counteracting the effects of angiotensin II in states with excessive activation of the renin-angiotensin system such as hypertension (HTN), heart failure (HF) and atherosclerosis." (PMID 33748827, 2020). "An impairment in pressure-natriuresis mechanisms leads to salt-sensitive hypertension, which shows a substantially increased incidence as age increases, leading to a higher prevalence of low-renin essential hypertension in older subjects." (PMID 32645850, 2020). "Twenty percent of patients with essential hypertension have suppressed plasma renin activity, which indicates a volume expanded state." (PMID 32992705, 2020). "These mice develop typical signs of HF, including activation of the renin–angiotensin–aldosterone system, cardiac hypertrophy, high blood pressure, and increased levels of atrial natriuretic peptide." (PMID 32911795, 2020). "A study in 13 essential hypertensive patients who received long-term clonidine showed that it lowered plasma renin activity, modulated renal vascular resistance, and subsequently lowered MAP." (PMID 32613001, 2020). "The blockade of the renin-angiotensin (RAA) system revealed that the most significant effect on the emergence of essential hypertension has RAA activation." (PMID 32397357, 2020). "Increased RAS activity by a VDR-mediated effect leads to increased renin levels, resulting in increased plasma ATII levels which cause hypertension in mice." (PMID 32039229, 2019). "These mice display high aldosterone and low renin levels, marked hypertension, hypokalemia, and signs of incipient kidney damage." (PMID 31615979, 2019). "With the profound increases in Na+ retention observed in the various models of fructose-induced hypertension with expected extracellular volume expansion, it would be anticipated that plasma renin activity (PRA) would be suppressed." (PMID 30866441, 2019). "Work Up: A strong family history of hypertension, suppressed renin/aldosterone levels and response to ENaC antagonism is highly suggestive, but a definitive diagnosis requires genetic testing." (PMID 31312622, 2019). "As well as JGA-mediated control of renal renin, there is an iRAS that also plays a role in sodium homeostasis and hypertension through its effects on renal vascular resistance." (PMID 31551925, 2019). "Constitutive activation variants of SCNN1B or SCNN1G result in salt-sensitive hypertension known as Liddle’s syndrome, an autosomal dominant form of monogenic hypertension that is characterized by early-onset of low-renin hypertension." (PMID 30832344, 2019).
Hypertension (continued). "Clcn2op mice display typical features of human PA, including high serum aldosterone in the presence of low renin activity, marked hypertension and hypokalemia." (PMID 31615979, 2019). "The pathogenesis of hypertension involves an increase in sympathetic nervous system activity and renin-angiotensin-aldosterone system activity." (PMID 31318924, 2019). "20-HETE was a CYPs hydroxylase-derived metabolite of AA, involved with the renin-angiotensin system (RAS) to promote hypertension, vasoconstriction, and vascular dysfunction." (PMID 31592228, 2019). "The role of excessive renin secretion in relation to volume status and sodium hasbeen recognized as an important factor in the pathogenesis of hypertension indialysis patients." (PMID 30421784, 2019). "A crucial pathological feature in hypertension and eventually heart failure is the sustained activation of endogenous neurohormonal systems, particularly renin-angiotensin-aldosterone system (RAAS)." (PMID 31157242, 2019). "Male hormones exert a deleterious effect in terms of activating the renin-angiotensin system (RAS), stimulating endothelin synthesis, and increasing oxidative stress, which are closely associated with hypertension and renal injury." (PMID 31818273, 2019). "Its most frequent side effect is pseudohyperaldosteronism, a clinical condition characterized by hypertension, hypokalemia and suppression of plasma renin and aldosterone levels." (PMID 31379750, 2019). "The authors reported that 1α(OH)ase null mutant mice presented hypertension, increased renin, ANGII and AT1 receptor levels and increased malondialdehyde in the brain, together with compromised antioxidant expression." (PMID 31380328, 2019). "Arterial hypertension is induced and maintained by a complex network of systemic signaling pathways, such as the hormonal axis of the renin-angiotensin-aldosterone system, hemodynamic alterations affecting blood flow, oxygen supply, and the immune system." (PMID 31052201, 2019). "Hypertension can also stimulate arteriogenesis through the increase of shear stress and activation of the renin-angiotensin system." (PMID 31362356, 2019). "Its cardinal role in the development of hypertension is evidenced by the increases in blood pressure in mice with renin overexpression." (PMID 31680980, 2019). "We compared the effects of HS plus captopril (CAP) coadministration to HS and CAP administration alone on blood pressure and renin-angiotensin-aldosterone system (RAAS) biomarkers in the rat two-kidney-one-clip (2K1C) model of hypertension." (PMID 31379972, 2019). "Further, there is an important contribution to the hypertension from miR-181a and renal renin in this strain." (PMID 31681017, 2019). "Budget impact analysis of increasing uptake of renin-angiotensin system inhibitors (RAS) drugs to standard anti-hypertensive treatments for patient with hypertension and diabetes in Malaysia." (PMID 30817790, 2019). "When age, sex, duration of hypertension, and BMI were matched between groups, snoring patients still showed significantly (P < 0.05) higher plasma renin activity, serum and urinary sodium, and lower ARR and eGFR than those in the PA-only group." (PMID 31089199, 2019). "As expected, there is clear evidence for the association of hypovitaminosis D with hypertension and RAS over-activity, whilst vitamin D treatment can lower human blood pressure by suppressing renin formation, reducing RAS activity." (PMID 31284538, 2019). "She initially presented as primary hyperaldosteronism with hypertension, persistent hypokalemia, and an elevated aldosterone/plasma renin activity ratio." (PMID 31500669, 2019). "Expression of ACE is induced along with the induction of renin synthesis in the CD during Ang II-dependent hypertension." (PMID 31680980, 2019). "In a preliminary abstract report, BPH/2 mice treated with a miR-181a mimic had a reduced level of hypertension and normalized levels of renal renin expression." (PMID 31681017, 2019).